BRCA2 (BRCA2 DNA repair associated)
Diseases named in the same sentence as BRCA2 in open-access papers (continued):
Sharing a sentence is not in itself a finding about the gene and the disease.
tumor (continued). "This percentage was significantly higher for the gains of the BRCA1-mutated tumor group but not for the BRCA2-mutated tumor group when compared to the sporadic control tumors (p = 2.5 × 10-3 calculated with t-test with unequal variance)." (PMID 20735817, 2010). "Tumours from BRCA1 and BRCA2 mutation carriers display distinctive pathological features that could be used to better discriminate between BRCA1 mutation carriers, BRCA2 mutation carriers and noncarriers." (PMID 20482762, 2010). "The DNA from microdissected FFPE tumour tissue was available from 5 of 6 germline BRCA2 carriers." (PMID 20736950, 2010). "The average amount of gains and losses in the BRCA2-mutated tumor group was not significantly increased compared with the control group except between thresholds of 0.06 and 0.08." (PMID 20735817, 2010). "These sporadic tumours behave like BRCA1 and BRCA2 deficient tumours but do not possess germ line mutations in either gene." (PMID 24281034, 2010). "The one sporadic tumour that clustered among the BRCA2-related subgroup displayed gains in copy numbers of the EMSY gene located at 11q13.5, which was confirmed by FISH analysis for two different regions of the tumour showing gene/centromere ratios of 1.9 and 3.0, respectively." (PMID 19589159, 2009). "BRCA2 protein expression also frequently varied between paired primary and recurrent neoplasms." (PMID 19602291, 2009). "This tumour displayed a deletion at the BRCA2 gene locus and gains in EMSY gene copy numbers." (PMID 19589159, 2009). "The BRCA2-related subgroup was entirely composed of luminal tumours (9 of 9, 100%)." (PMID 19589159, 2009). "This raises the possibility that the natural history of some familial BRCA2 tumours does not involve loss of the wild-type BRCA2 allele or at least only partial loss as has been suggested before." (PMID 19589159, 2009). "Importantly, we show that the development of a subset of sporadic tumours is similar to that of either familial BRCA1- or BRCA2 tumours." (PMID 19589159, 2009). "Taken together, this suggests that a small subset of BRCA2 tumours could be promoted by haploinsufficiency for the BRCA2 gene." (PMID 19589159, 2009). "Indeed chromosome 13 harbors tumour suppressor genes such as BRCA2 (13q12.3) and retinoblastoma gene (RB1) (13q14)." (PMID 17908304, 2007). "According to this definition, 31.1% (42/135) of informative tumours had AI at the BRCA2 locus." (PMID 16846527, 2006). "Although mutations in BRCA2 do not provide a growth advantage in nonneoplastic cells, the BRCA2 gene is often discussed as a "tumor-suppressor" gene." (PMID 16417627, 2006). "This raises the possibility that the initial stages of tumour formation in BRCA1 and BRCA2 mutation carriers are hormone dependent, in which case early endocrine therapy might be an effective prevention strategy." (PMID 16538216, 2006). "We know, for instance, that unlike with germline mutations of the gatekeeper genes APC, MEN1 and RB1, the germline BRCA2 mutations do not give rise to a recognizable syndrome of multiple incipient neoplasms in any particular organ." (PMID 16417627, 2006). "However, among both BRCA1 and BRCA2 families, tumours from older patients form subgroups that are distinctly different from those of the younger patients." (PMID 15987451, 2005). "However, tumours of BRCA2 carrier patients diagnosed at 50 years or older had more distinctive features, and were more ER- and PR-, than tumours of younger patients or tumours of the same age group of BRCA1 patients or non-BRCA1/2 patients." (PMID 15987451, 2005). "The LOH data support the concept that BRCA2 behaves as a tumor suppressor gene." (PMID 16280055, 2005). "The specific features of BRCA1-associated tumours among the younger age group, and lack of such features among the BRCA2-associated tumours, are consistent with the overall characteristics reported previously among BRCA1 and BRCA2 patients." (PMID 15987451, 2005).
tumor (continued). "LOH at BRCA2 was also associated, albeit non-significantly, with large tumour size and the ductal and medullar histological types." (PMID 8932343, 1996). "Moreover, a few tumours demonstrated a restricted deletion pattern, suggesting the presence of additional tumour-suppressor genes both proximal and distal of BRCA2." (PMID 8932343, 1996). "However, in the BRCA2-mutant tumor line PEO1, A3B loss did not significantly rescue drug sensitivity." (PMID 41162355, 2025). "The complete loss of the olaparib effect in the Brca2(−/−) model (in contrast to the Brca2(−/−)* model) could be due to tumour-promoting immune cells still being attracted to the Brca2(−/−) model by intact chemokine secretion in athymic mice lacking mature T cells." (PMID 40579444, 2025). "In addition, the inherently high baseline genomic instability in BRCA2-mutant tumor lines may render them intrinsically hypersensitive to HU and cisplatin, limiting the extent of rescue achievable by siRNA-mediated A3B depletion alone." (PMID 41162355, 2025). "Moreover, the involvement of BRCA1 and BRCA2 in other cellular functions—such as chromatin remodeling and regulation of gene transcription—may further influence tumor development." (PMID 41373813, 2025). "Despite the fact that CTCs are difficult to be unquestionably identified as tumor cells, they are frequently associated with invasiveness and treatment resistance, and in our analysis an EMT CTC overexpressed DNA repair genes, consistent with platinum sensitivity and BRCA2/PALB2 status." (PMID 41367869, 2025). "Interestingly, two cases with germline BRCA2 variants not having BRCA2 LOH in the tumor showed no signs of chromosomal instability (score = 0)." (PMID 41465280, 2025). "PEO1 was established when the tumor initially responded to PARP inhibitor treatment, and PEO4 cells are derived from the same patient when her tumor became PARPi resistant, which occurred when the original mutation in BRCA2 (Y1655* nonsense mutation) reverted to BRCA WT function." (PMID 40915175, 2025). "Notably, the family history was negative, and the tumor displayed allelic loss at the BRCA2 locus and was MSS." (PMID 39102164, 2024). "They found that compared with those without mutation, those with BRCA2 mutation had significantly larger tumor diameter (2.7 cm vs 2.4 cm, P < 0.001), higher lymph node-positive rate (55% vs 43%, P = 0.001), and higher incidence of second or contralateral BC (18.6% vs 6.7%, P < 0.001)." (PMID 38184581, 2024). "Thus, BRCA2 functions as a tumor suppressor by maintaining genomic stability." (PMID 38271119, 2024). "Finally, the ‘other’ category provided informative evidence towards variant pathogenicity for both BRCA1 (LR: 3.62 (95% CI: 2.61–5.03), supporting evidence) and BRCA2 (LR: 3.46 (95% CI: 2.20–5.43), supporting evidence), if tumours were undifferentiated or poorly differentiated." (PMID 37076566, 2023).
tumor (continued). "Thus, our findings suggest that loss of a single Brca2 allele in an unchallenged (i.e., absent additional known tumour driver mutations or genotoxic exposures) mammary gland does not affect the generation or maintenance of epithelial lineages." (PMID 37626143, 2023). "We have studied the circular RNA/messenger RNA pair in BRCA1- and BRCA2-related breast tumorigenesis using an innovative dedicated technique and have shown for the first time that there is an imbalance in the circular RNA/messenger RNA ratio between healthy and tumor breast tissues." (PMID 37046838, 2023). "Brca2 was mutated in the five tumours arising from the same liver but not in the other livers." (PMID 37663116, 2023). "Moreover, it has been shown that in a certain group of patients with BRCA1/BRCA2 wild type, they present an immune profile of the tumor showing the expression of PD-1/PDL-1 that would benefit from the treatment of iPARP associated with immunotherapy directed at these two biomarkers." (PMID 37444580, 2023). "Notably, HuR levels were even higher in BRCA1 (63%) and BRCA2 (62%) tumours and associated with a non-significant reduction in survival in BRCA2 mutation carriers." (PMID 36831687, 2023). "In contrast, monogenic BRCA2 or RAD51C tumor mutations confer only a minor but insignificant decrease in overall survival compared to patients with no BRCA2 or RAD51C mutation, revealing genetic vulnerability associated with the polygenic BRCA2 + RAD51C mutations." (PMID 36906610, 2023). "We noted for non-BRCA1/BRCA2 tumours, only a small proportion displayed high HRDetect scores and were characterized by concomitant promoter hypermethylation or in one case a RAD51D splice variant previously reported as having unknown significance to potentially explain their BRCAness." (PMID 37316882, 2023). "NGS analyses revealed that the CN of BRCA2 and RB1 in adjacent normal prostate tissues was not decreased in 10 patients with PC with tumor BRCA2 alteration, suggesting that in the present study, BRCA2 and/or RB1 deletions were caused by somatic gene alterations." (PMID 36645189, 2023). "Next, we tested whether expression of BRCA2-001/Short affected overall survival across 67 BRCA1/2 mutation carriers (from discovery and validation cohorts) for whom we had survival data and RNA sequenced from at least one tumor." (PMID 36344544, 2022). "However, the associations between these genes and an HRD phenotype may be less consistent than those for BRCA1 and BRCA2 and may vary by the tumor’s tissue of origin." (PMID 35740616, 2022). "Yet the precise mechanism by which BRCA2 exerts its tumor suppressor function remains unclear." (PMID 35734584, 2022). "For the tumor with a somatic BRCA2 mutation with LOH (M096), which was not identified as HRD by the BRCA1/2-like classifier and CHORD, the normal control was shown to contain significant contamination with tumor DNA, which is likely to have compromised the somatic mutation calling." (PMID 35662281, 2022). "Among the 760 tumor samples successfully sequenced, 178 (23.4%) cases harbored a pathogenic/likely pathogenic (P/LP) mutation, 74 (9.7%) cases showed a variant of uncertain significance (VUS) only, and 508 (66.8%) were defined as BRCA1 and BRCA2 wild type (wt)." (PMID 35406410, 2022). "Therefore, iNOS-induced NO indirectly suppresses BRCA1 and BRCA2 tumor suppressor functions." (PMID 35740092, 2022). "This explanation could be valid for the three tumors with BRCA1 promoter methylation and the tumor with a somatic BRCA2 mutation with LOH, which were not identified as HRD by BRCA1/2-like classifier and both BRCA1/2-like classifier and CHORD, respectively." (PMID 35662281, 2022).
tumor (continued). "Thus, understanding BRCA2 function as a tumor suppressor will be aided by defining the individual role(s) of domains within unknown regions of the protein." (PMID 34356050, 2021). "However, as the two neoplasms showed neither loss of heterozygosity nor somatic mutation in the second BRCA2 allele, they cannot be considered as BRCA-dependent tumors." (PMID 33810291, 2021). "Importantly, only three out of fifteen patients with deleterious DDR alterations harbored tumor mutations in BRCA1 or BRCA2 and no information is provided on the responses of these three patients." (PMID 34067105, 2021). "Moreover, we found tumor suppressor-BRCA2 had a positive correlation with p53BER2; further experiments showed the p53BER2 could induce cell-cycle arrest and DNA repair by mediating BRCA2." (PMID 33414393, 2021). "Thus, an accurate comprehension of how BRCA2 functions as a tumor suppressor will likely require defining the specific roles of known, and still unknown, domains throughout the protein." (PMID 34356050, 2021). "Therefore, we tested LOH in c.9976A>T carrier cases where c.9976A>T occurred without any other pathogenic BRCA1 or BRCA2 variant and where a tumor sample was available." (PMID 33672545, 2021). "This hypothesis is reinforced by the intrinsic subtypes of BRCA1, BRCA2 and BRCAx tumours." (PMID 33081408, 2020). "Therefore, it became important to evaluate whether a tumor-testing-first strategy would be the most cost-effective option, allowing for the simultaneous detection of both germline and somatic BRCA1/BRCA2 variants." (PMID 32850417, 2020). "However, sequencing of BRCA1 and BRCA2 requires the analysis of a number of amplicons—too large to be added to a panel like ours—designed to cover relevant markers for the largest possible number of tumor types following the needs of our medical center." (PMID 32340363, 2020). "Furthermore, African American patients show a higher mutation frequency of BRCA1 (10.2%) and BRCA2 (5.7%) tumor suppressor genes comparing to European non-Ashkenazi Jews White patients (BRCA1: 6.9%, BRCA2: 5.2%)." (PMID 32873298, 2020). "Similarly, the 11-gene BRCA2-related list correctly classified 82% (18/22) of tumours." (PMID 33081408, 2020). "In contrast, there was no obvious tumor subtype associated with BRCA2 variant carriers." (PMID 33067557, 2020). "Assuming that clinically significant tumours are likely to be diagnosed regardless of screening regimen, this observation is consistent with the hypothesis that BRCA2 mutations are associated with a risk of more aggressive disease." (PMID 31495749, 2020). "Indeed, in MMR-deficient tumors but not in MMR-proficient tumors, frameshift mutations in mononucleotide tracts have been identified in tumor suppressors and DNA repair genes such as BRCA1, BRCA2 and BLM80,81, and tumor progression genes such as BAX82 and TGFB283." (PMID 33299637, 2020). "Since BRCA1/BRCA2 tumor testing can detect simultaneously both somatic and germline variants, with the exception of some variants like rearrangements, a higher number of patients who may benefit from PARPi can be identified at a faster turnaround time and at a lower cost." (PMID 32850417, 2020). "We found that both BRCA1 and BRCA2-mutated tumors had significantly more indels (Wilcoxon test, p = 1.6 × 10− 5 for BRCA1 and p = 1.4 × 10− 3 for BRCA2) and structural variants (Wilcoxon test, p = 5.1 × 10− 7 for BRCA1 and p = 0.029 for BRCA2) per tumor than the sporadic tumors." (PMID 31182087, 2019).
tumor (continued). "Having shown that DNA damage is increased in olaparib-resistant tumours, we next analysed whether HRR could have been restored to repair this damage, although unlikely in our model, given the permanent nature of deletion of the Brca2 conditional allele." (PMID 31080552, 2019). "Hence, to circumvent the embryonic lethality and to study the role of these tumor suppressors in pancreatic development and malignant transformation, we specifically deleted Palb2, Brca1 or Brca2 in the pancreas only using the Cre-LoxP recombination technology." (PMID 31877165, 2019). "Thus, we used BRCA2+/+ and BRCA2−/− DLD1 cells to generate xenograft tumours in mice." (PMID 31273933, 2019). "The differential analysis filtered for processes driven by CD271 in tumor-initiating cells also revealed enrichment for the genes participating in nucleotide excision repair (NER, including damage recognition and repair factor XPC, DNA repair associated BRCA2, UBE2I, COPS7A, POLD3, USP45, RFC5)." (PMID 31118427, 2019). "First, the reduction in full‐length BRCA2 mRNAs in variant carriers compared to normal controls, which was not statistically significant, might not be enough to affect cellular tumor suppressor ability." (PMID 29460995, 2018). "Two patients presented more than one (missense) VUS in BRCA2 gene, one of them, diagnosed with a triple negative tumor reported a positive family history (c.3349A>G; c.5414A>G; c.8092G>A); the other one, diagnosed with a luminal B tumor, presented a limited family history (c.2837A>G; c.7418G>A)." (PMID 29854292, 2018). "In addition, in a cohort of 560 individuals with BC, HRDetect identified 22 tumours with somatic loss-of-BRCA1 or BRCA2 and 47 tumours with functional BRCA1/2 deficiency, none of which had mutations detected with standard analysis." (PMID 29867226, 2018). "However, considering BRCA1 and BRCA2 were thought be tumor suppressor proteins, it is alarming that the inhibitory effect of curcumin on the expression of BRCA1 and BRCA2 in T241 cells might lead to tumor progression." (PMID 29255221, 2017). "The results of subgroup analyses for OS stratified by study quality, tumor stage, study design, sample size, number of research center, duration of follow-up, baseline characteristics adjusted and tumor histology were mostly constant across BRCA1/2, BRCA1 and BRCA2 mutation subtypes." (PMID 27690218, 2017). "In contrast, NGS of the liver metastasis revealed a deletion in chromosome 13q, including BRCA2, RB1 and ERRC5, accounting for the allele containing the germline BRCA2 p.W563* mutation, which was only present in 4% of sequencing reads (in a sample with 90% tumor content)." (PMID 29262651, 2017). "Among the 20 somatic-BRCA1/2-mutated tumor samples, there was one heterozygous BRCA2 mutation that lacked clear biallelic inactivation at the time of archival tumor collection prior to the Study 19 trial and two BRCA2 mutations predicted as subclonal somatic by the SGZ algorithm." (PMID 28525389, 2017). "However, tumours harbouring wild-type BRCA2 or BRCA2-deficient tumours with BRCA2 overexpression did not respond to the treatment." (PMID 27686855, 2016). "In a study including 50 male BRCA1/2 mutation carriers, it was suggested that BRCA2 MBCs may represent a subgroup of tumours with a peculiar phenotype not identified in FBC and characterised by an aggressive biological behaviour." (PMID 26857456, 2016).